CD74 (CD74 molecule)
Diseases named in the same sentence as CD74 in open-access papers (continued):
Sharing a sentence is not in itself a finding about the gene and the disease.
clear cell renal cell carcinoma (7 papers, 2014 to 2026). "High glucose, metabolic mediators of injury, nephrotoxins and cytokines increase the expression of CD74 in renal cells to cause kidney injury and is also highly up-regulated in clear cell renal cell carcinoma." (PMID 29296203, 2017). "The sKGs, CD74 expression in clear cell renal cell carcinoma (ccRCC) cells has shown to be significantly associated with high infiltration of CD4 + T cells, which may have important implications for the tumor microenvironment and immune response." (PMID 40834023, 2025). "In clear cell-renal cell carcinoma, the tumor grade was related to CD74 expression, and downregulation of CD74 induced cell cycle arrest and apoptosis, while cell proliferation and invasion were suppressed." (PMID 27626171, 2016). "It was reported that CD74 played critical role in cancer cell tumorigenesis and downregulation of CD74 inhibits growth and invasion in clear cell renal cell carcinoma." (PMID 26346000, 2015). "MIF, MIF-2, CD74, and CD44 promote clear cell renal cell carcinoma, cell proliferation, and HIF-activation." (PMID 26441987, 2015). "In vitro studies on MIF/CD74 (CD44) knockdown by siRNA approach, as reported for clear cell renal carcinoma, shed light on this aspect." (PMID 24939415, 2014).
colon cancer (7 papers, 2014 to 2023). "The mentioned CD74 signature, that is associated with colon tumors with MSI-H and with the colon cancer subtype termed CMS1 (that represents 14% of all tumors), has been characterized as MSI Immune and it is known to be hypermutated and microsatellite unstable." (PMID 36975409, 2023). "MIF and its receptor, CD74, were examined in gastric and colon tumors and found to be increased in most tumors with significantly higher expression in tumors from patients with lymph node metastasis." (PMID 24887129, 2014). "CD-74 has been recognized in the colon as a potential biomarker for colon cancer." (PMID 37763280, 2023). "We also found that patient gastric and colon tumors expressing the highest levels of MIF and CD74 to be from patients with nodal involvement, thus suggesting an association with more aggressive disease." (PMID 24887129, 2014). "Finally, we observed that the mentioned CD74 signature correlated with MSI-H tumors and the colon cancer subtype CMS1 that represents 14% of the tumors and is associated with immune strong activation." (PMID 36975409, 2023). "The heatmaps of CD44 mRNA in colon cancer were strikingly opposite to CD4 and CD74." (PMID 27323782, 2016).
diabetic nephropathy (7 papers, 2012 to 2024). "The serum MIF concentration is elevated in T2DM individuals 19 and MIF and CD74 are two overexpressed genes in human diabetic nephropathy." (PMID 25661015, 2015). "CD74 expression is regulated in aged rats, and its expression is also increased in Pima Indians with diabetic nephropathy." (PMID 23947592, 2013). "CD74, the macrophage inhibitoryfactor receptor, is a potent receptor of kidney injury in diabetic nephropathy." (PMID 23007467, 2012). "The factors known to upregulate CD74 expression in kidney cells may be relevant for diabetic nephropathy, Fabry disease, and inflammatory conditions." (PMID 26441987, 2015). "CD74 is a multifunctional protein and a receptor for Macrophage Migration Inhibitory Factor (MIF) and MIF-2 / D-dopachrome tautomerase (DDT) cytokines, upregulated in diabetic kidney disease." (PMID 29924850, 2018). "CD74 is upregulated in tubular epithelial cells in at least some forms of chronic kidney disease (CKD), such as kidney graft rejection, diabetic and Fabry nephropathy and autosomal dominant polycystic kidney disease (ADPKD), and in podocytes in human diabetic nephropathy and Fabry nephropathy." (PMID 26441987, 2015).
invasive breast carcinoma (7 papers, 2009 to 2024). A carcinoma that infiltrates the breast parenchyma. "We have shown that CD74 expression is associated with better prognosis in Basal-like subtype invasive breast cancer." (PMID 27058619, 2017). "Our results are also consistent with the previously demonstrated prognostic influence of CD74 on survival in patients with other types of malignancies, such as in basal-like subtype invasive breast cancer." (PMID 33327409, 2020). "Expression of CD74 on tumor cells has been associated with higher MHC class II expression and a stronger intratumoral immune response in basal-like invasive breast cancer." (PMID 31693710, 2019). "Previous studies have shown that CD74, the γ chain of HLA class II antigens, increases during invasive breast cancer." (PMID 27857940, 2016). "The in vitro studies suggested that exogenous MIF derived from the tumour microenvironment promotes proliferation, adhesion, and invasion of CD74+ invasive breast cancer cells." (PMID 19602265, 2009).
ovarian carcinoma (7 papers, 2013 to 2025). A malignant neoplasm originating from the surface ovarian epithelium. "The CD74, CXCL1, and IL-6 released from surrounding cancer-associated mesenchymal stromal cells (CA-MSCs) have been reported to increase cancer stem cells of ovarian cancers." (PMID 40507922, 2025). "Based on expression of 21 CAF‐associated markers, we defined four subtypes of CAFs in ovarian cancer as follows: myofibroblast CAFs (myCAFs, 0: SMA+, 1: FAP+, 2: COL1A1+) and antigen‐presenting CAFs (apCAFs, 3: CD74+/HLA‐DRA+)." (PMID 40126173, 2025). "Among the genes that were highly expressed and commonly significant LR pairs in both the R and NR groups, CD74, GAS6, and VEGFA were associated with carcinogenesis and were prominent markers of targeted therapy in ovarian cancer." (PMID 39135097, 2024). "Although each alteration is infrequent, ROS1 fusions with many kinds of 5′ partner genes (CCDC6, CD74, EZR, KDELR2, LRIG3, SDC4, SLC34A2 and TPM3) have been reported in lung, brain, biliary tract, and ovarian cancers." (PMID 23418494, 2013). "The expression of CD74 has been investigated in several types of cancer, but not ovarian cancer." (PMID 38534733, 2024).
diabetes (6 papers, 2012 to 2025). "Furthermore, in studies on patients with diabetes, CD74 was also identified as a microglial activation marker." (PMID 34576123, 2021). "In order to evaluate the potential in vivo relevance of MIF/CD74 pathway during T1D, we investigated whether targeting MIF could prevent diabetes transfer by autoimmune NOD splenocytes into NOD.SCID mice." (PMID 29095944, 2017).
Insulin resistance (6 papers, 2020 to 2025). Increased resistance towards insulin, that is, diminished effectiveness of insulin in reducing blood glucose levels. "Genes commonly upregulated in the IR-iPSCs when compared to each IS-iPSC group include EGR1 and MFGE8, which were previously associated with insulin resistance, as well as CD74, SEMA6B, SLFN13, TMEM151B, SLC22A17, and AGRN." (PMID 35987697, 2022). "One such novel prediction is CD74 for insulin—this gene’s role in insulin secretion and related diseases was not well-established until the recent discovery of its participation in insulin resistance." (PMID 37093889, 2023).
renal fibrosis (6 papers, 2016 to 2024). A final common manifestation of a wide variety of chronic kidney diseases characterized by glomerulosclerosis and tubulointerstitial fibrosis. "Our results have suggested that AOAH protected against renal fibrosis by inhibiting CD74 signaling pathway, the precise mechanism underlying the interaction between AOAH and CD74, however, remains unknown." (PMID 38904010, 2024). "Furthermore, our results demonstrated a positive association between CD74 expression and renal fibrosis." (PMID 38904010, 2024). "In this study, we investigate the roles and mechanisms of upregulation of CD74 in promoting cyst growth and renal fibrosis in ADPKD." (PMID 38534333, 2024). "By screening genes through databases related to renal fibrosis, two core genes, SUMO3 and CD74, were identified to have a causal relationship with DKD, highlighting their strong predictive accuracy in the validation dataset." (PMID 39398062, 2024). "To investigate how MIF regulates renal fibrosis through CD74, we treated rat renal fibroblast NRK-49F cells with either MIF or ISO-1." (PMID 38534333, 2024). "We show that knockout of CD74 ameliorates cyst growth and renal fibrosis in Pkd1 mutant mouse kidneys." (PMID 38534333, 2024). "Knockout of MIF also decreases renal fibrosis in Pkd1 mutant mouse kidneys, and knockdown of CD74 blocks MIF induced the expression of fibrotic markers, supporting a novel mechanism that MIF is through CD74 to regulate the transcription of fibrotic markers followed by renal fibrosis." (PMID 38534333, 2024). "In this study, CD74 was closely correlated with the process of renal fibrosis and could be a biomarker for mechanism studies in the future." (PMID 36523757, 2022). "However, the role and mechanisms of CD74 in regulation of cyst growth and renal fibrosis in ADPKD remain unknown." (PMID 38534333, 2024). "Our study suggests that MIF triggers the activation of TGF-β-Smad signaling in a CD74 dependent manner via CD74 mediated the transcription regulation of TGF-β and fibrotic marker genes to regulate renal fibrosis in ADPKD kidneys." (PMID 38534333, 2024). "Here, we have demonstrated increased CD74+ PTECs as well as elevated CD74 expression in FA-induced renal injury model with the lack of Aoah, and suggested that AOAH plays a protective role in renal fibrosis by inhibiting CD74 signaling pathways." (PMID 38904010, 2024). "CD74 regulates the transcription of fibrotic genes, including Col I, fibronectin and α-SMA through binding to their promoters, and the activation of TGF-β-Smad3 signaling to increase renal fibrosis in ADPKD kidneys." (PMID 38534333, 2024). "As CD74 is a major receptor of MIF, we hypothesize that targeting MIF should also decrease renal fibrosis in ADPKD kidneys." (PMID 38534333, 2024). "However, little evidence exists concerning the involvement of CD74 signaling machinery in renal fibrosis." (PMID 38904010, 2024).
rheumatoid arthritis (6 papers, 2021 to 2026). A chronic, systemic autoimmune disorder characterized by inflammation in the synovial membranes and articular surfaces. "The blockade of CD74 expression and its partner macrophage migration inhibitory factor has been applied as a targeted therapy for autoimmune encephalomyelitis and rheumatoid arthritis." (PMID 40761479, 2025). "In addition, the three genes (PSMB9, CD74, and HLA-F) were validated in other rheumatologic disorders including systemic lupus erythema (SLE) and rheumatoid arthritis (RA)." (PMID 37153570, 2023).
ankylosing spondylitis (5 papers, 2015 to 2023). An autoimmune chronic inflammatory disorder characterized by inflammation in the vertebral joints of the spine and sacroiliac joints. "It has even been documented that MIF induces TNF production in monocytes, activates β-catenin in osteoblasts and promotes the mineralization of osteoblasts, indicating that the MIF/CD74 axis is linked to inflammation and new bone formation seen in ankylosing spondylitis." (PMID 34621738, 2021). "Ankylosing spondylitis (AS) is associated with autoantibody production to class II MHC‐associated invariant chain peptide, CD74/CLIP." (PMID 32198923, 2020). "Autoantibodies against CD74 (anti-HLA class II-associated invariant chain peptide, CLIP) were found in 67% of ankylosing spondylitis patients, in 15% of systemic lupus erythematosus patients, and only in 0.8% of blood donors." (PMID 26441987, 2015). "Ankylosing spondylitis (AS) patient sera contain anti‐CD74 autoantibodies." (PMID 32198923, 2020).
autoimmune liver disease (5 papers, 2016 to 2025). "A soluble variant of CD74 was discovered in autoimmune liver disease, in which membrane-truncated CD74 is released after proteolytic processing." (PMID 41439980, 2025). "In addition, soluble CD74 (sCD74) is a membrane truncated protein that has been shown to be associated with a variety of diseases, such as autoimmune liver disease, acute respiratory distress syndrome, burn injury, myocardial ischemia-reperfusion (I/R) injury, and myocardial fibrosis." (PMID 36712241, 2022). "sCD74, a truncated form of the extracellular domain of CD74, was first identified in autoimmune liver disease and subsequently in patients with heart failure and MI, yet its specific role in disease progression remains to be further explored." (PMID 36712241, 2022). "A circulating form of CD74 (soluble CD74, sCD74) was recently discovered in autoimmune liver disease." (PMID 27444250, 2016).
cyst (5 papers, 2015 to 2024). A sac-like closed membranous structure that may be empty or contain fluid or amorphous material. "We found that knockout of CD74 delayed cyst growth in kidneys from Pkd1flox/flox:Ksp-Cre:CD74−/− mice (n = 9) at postnatal day 7 (PN7) compared to that in age matched Pkd1flox/flox:Ksp-Cre:CD74+/+ mice (n = 7)." (PMID 38534333, 2024). "MIF activates CD74 to increase inflammatory cytokines in podocytes and tubular cells and proliferation in glomerular parietal epithelial cells and cyst cells." (PMID 26441987, 2015). "We show that knockout of CD74 delays cyst growth in Pkd1 mutant kidneys." (PMID 38534333, 2024). "Interestingly, CD74 also regulates the transcription of MIF to form a positive feedback loop in that MIF binds with its receptor CD74 to regulate the activity of intracellular signaling pathways and CD74 increases the expression of MIF in ADPKD kidneys during cyst progression." (PMID 38534333, 2024). "Our results suggested that MIF may be through its receptor CD74 to promote interstitial fibrosis in ADPKD kidneys, and targeting MIF with ISO-1 should ameliorate not only cyst growth but also interstitial fibrosis." (PMID 38534333, 2024). "Knockout of CD74 decreased cyst index, kidney weight to body weight ratios (KW/BW) and blood urea nitrogen (BUN) in Pkd1flox/flox:Ksp-Cre:CD74−/− mice compared to those from Pkd1flox/flox:Ksp-Cre:CD74+/+ mice." (PMID 38534333, 2024). "Cd74 could be activated using the macrophage migration inhibitory factor (MIF) to increase inflammatory cytokines in podocytes and tubular cells, along with proliferation in glomerular parietal epithelial cells and cyst cells." (PMID 33779731, 2021).
experimental autoimmune encephalomyelitis (5 papers, 2015 to 2024). An autoimmune demyelinating disease of the central nervous system that is produced experimentally in animals by the injection of homogenized brain or spinal cord in Freund's adjuvant. "In cases of MS, CD74 was expressed in pre-active and remyelinating lesions, and interestingly, blocking CD74 in an experimental autoimmune encephalomyelitis (EAE) model ameliorated the symptoms in mice." (PMID 34571885, 2021). "We previously demonstrated enhanced CD74 cell surface expression on monocytes in mice with experimental autoimmune encephalomyelitis (EAE)." (PMID 26104759, 2015). "(G, I) Representative images of RNAscope labeling for (G) Fcgr3, B2m, Cd74, and (I) Gfap, C3 in Swiss Jim Lambert (SJL) mice 11 weeks after experimental autoimmune encephalomyelitis (EAE) induction." (PMID 39475792, 2024).
liver cancer (5 papers, 2023 to 2025). An epithelial or non-epithelial malignant neoplasm that arises from the liver. "Both MIF (macrophage migration inhibitory factor) and CD74 (CD74 molecule) were found spatially expressed and distributed in many tumor tissues, including liver cancer, intestine injured tissue and pancreas." (PMID 36243975, 2023). "Subsequently, the TIMER database was used to determine whether CD74 expression in liver cancer was related to the level of immune cell infiltration." (PMID 39118044, 2024). "In b_ILC1-XCL1, which is similar to the ILC2a cells found in liver cancer, genes such as XCL1, TCF7, and CD74 were highly expressed." (PMID 37762493, 2023).
lymph node metastasis (5 papers, 2014 to 2024). "CD74 has been associated with B-cell proliferation and survival and lymph node metastasis." (PMID 39400127, 2024). "Multivariate logistic regression analysis of lymph node metastasis (LNM) factors in BIDC patients revealed that LNM was associated with the clinical stage and CD74 expression level." (PMID 27626171, 2016). "Taking these data together, we found that CD74 was highly expressed in BIDC, and the CD74 expression level was associated with both clinical stage and lymph node metastasis." (PMID 27626171, 2016). "In total, there were eighteen L‐R pairs decreased in NPC patients with lymph node metastasis, and the communication probability of five pairs including MIF‐(CD74 + CXCR4), MIF‐(CD74 + CD44), LGALS9‐CD45, IL16‐CD4 and CCL19‐CCR7 were increased in NPC_LNM." (PMID 39392128, 2024). "More specifically, the overexpression of the transmembrane glycoprotein CD74 has been significantly correlated with TNBC and lymph node metastasis." (PMID 33842315, 2021).
pancreatic ductal adenocarcinoma (5 papers, 2021 to 2024). An infiltrating adenocarcinoma that arises from the epithelial cells of the pancreas. "CD74 enhances neuroplasticity in the tumor microenvironment of pancreatic ductal adenocarcinoma via a complex signaling axis." (PMID 39118044, 2024). "The apCAFs expressing MHC class II and CD74 were reported in pancreatic ductal adenocarcinoma in 2019." (PMID 35784460, 2022). "Akt can also be upregulated by CD74 and potentiate the secretion of GDNF to promote the PNI process in pancreatic ductal adenocarcinoma." (PMID 38525111, 2024). "described, in pancreatic ductal adenocarcinoma, a novel population of cancer-associated fibroblasts (CAFs) that expressed MHC class II and CD74, but no classical co-stimulatory molecules and named it “antigen-presenting CAFs” (apCAFs)." (PMID 35432353, 2022).
preeclampsia (5 papers, 2015 to 2025). Preeclampsia is a hypertensive disorder of pregnancy that is characterized by new-onset hypertension with proteinuria presenting after 20 weeks of gestation, and depending on mild or severe forms may initially present with severe headache, visual disturbances, and hyperreflexia. "For example, reduced CD74 expression in placental macrophages has been associated with impaired macrophage–trophoblast interactions and heightened inflammatory responses in preeclampsia." (PMID 41425547, 2025). "Placentas from preeclampsia pregnancies have been reported to show lower expression of immune protein CD74 and enrichment for the IL-1-signaling pathway compared to uncomplicated placentas." (PMID 36550527, 2022). "RT-qPCR confirmed aberrant expression of genes involved in inflammation and stress response (TLR4 and TLR9) and also genes involved in host defense (PRDX5, MIF, CD74, NFE2L1, and CSF3R), suggesting that preeclampsia sera suppress the TLR4/9-dependent excess oxidative stress in adipose tissue." (PMID 26089598, 2015).
pulmonary hypertension (5 papers, 2016 to 2022). Increased pressure within the pulmonary circulation due to lung or heart disorder. "Treatment with the MIF antagonist ISO-1 or anti-CD74 neutralizing antibodies reduced inflammatory cell infiltration and, in addition, reversed the development of pulmonary hypertension in rats." (PMID 36553040, 2022). "Curative treatments with the MIF antagonist ISO-1 or anti-CD74 neutralizing antibodies partially reversed the development of pulmonary hypertension and substantially reduced inflammatory cell infiltration in the rat monocrotaline model of PAH." (PMID 33105588, 2020). "In experimental models, treatments with the MIF antagonist ISO-1 or anti-CD74 neutralizing antibodies partially reversed development of pulmonary hypertension in rats and substantially reduced inflammatory cell infiltration." (PMID 29728137, 2018). "As pulmonary hypertension and ED can both be treated with inhibitors of phosphodiesterase 5, CD74 may be another highly potent target for ED." (PMID 35518933, 2022).
sarcoma (5 papers, 2009 to 2025). A usually aggressive malignant neoplasm of the soft tissue or bone. "We found that C1QA (p = 0.025), CD74 (p = 0.017), and HLA-DMA (p = 0.007) were significantly associated with sarcoma patients’ OS." (PMID 38256356, 2024).